HSPA12A (heat shock protein family A (Hsp70) member 12A)
Description:
Adapter protein for SORL1, but not SORT1. Delays SORL1 internalization and affects SORL1 subcellular localization.
Synonyms: KIAA0417; FLJ13874
Tractability: PROTAC: ubiquitination databases record sites on it; its protein half-life has been measured.
Gene: Protein-coding gene on chromosome 10 (116,671,192 to 116,850,251, reverse strand). Ensembl gene ENSG00000165868.
Subcellular location: Cytoplasm; Nucleus
Subcellular location (Human Protein Atlas): Cytosol; Golgi apparatus
Pathways (Reactome):
Cellular responses to stimuli: Regulation of HSF1-mediated heat shock response
Gene Ontology:
Molecular function: protein binding
Cellular component: extracellular exosome; cytoplasm; nucleus
Genetic constraint (gnomAD): Loss-of-function variants: 28 observed, 64.39 expected, observed/expected ratio (o/e) 0.43, 90% interval 0.32 to 0.6. The upper end of that interval is the gene's LOEUF score, 0.6, which puts it in group 2 of 6, group 1 being the genes least tolerant of losing a copy. Missense variants: 684 observed, 912.48 expected, observed/expected ratio (o/e) 0.75, 90% interval 0.7 to 0.8. Synonymous variants: 345 observed, 378.65 expected, observed/expected ratio (o/e) 0.91, 90% interval 0.83 to 1.
Homologues: Orthologues: chimpanzee HSPA12A (98% identical), macaque HSPA12A (98% identical), rabbit HSPA12A (97% identical), dog HSPA12A (96% identical), guinea pig HSPA12A (96% identical), mouse Hspa12a (96% identical), rat Hspa12a (96% identical), tropical clawed frog hspa12a (82% identical), zebrafish hspa12a (79% identical), pig HSPA12A (70% identical). Paralogues in human: HSPA12B (63% identical), ALPK2 (14% identical), ALPK1 (14% identical), EEF2K (14% identical).
Diseases named in the same sentence as HSPA12A in open-access papers:
HSPA12A is named in the same sentence as 47 diseases in open-access papers, as found by Europe PMC text mining. Sharing a sentence is not in itself a finding about the gene and the disease. The quoted sentences say what the papers report.
breast carcinoma (4 papers, 2014 to 2026). "HSPA12A mRNA was down-regulated in bladder urothelial carcinoma, breast cancer, uterine corpus endometrial carcinoma and kidney renal papillary cell carcinoma." (PMID 34712697, 2021). "Another interesting observation from the present study is that several HSPs were downregulated in all breast cancer subtypes: DNAJB4, DNAJC18, HSPA12A, HSPA12B, HSPB2, HSPB6, and HSPB7." (PMID 29954368, 2018). "MCF10A cells exhibited significantly increased expression of HSP90AA1, CARHSP1, HSPA12A and decreased expression of HSPB1, HSPBL2, HSPA6, and HSPA7 (C vs H), while the three breast cancer lines showed no significant 2-fold or greater alterations in the expression of these genes (C’ vs H’)." (PMID 24511912, 2014).
colorectal cancer (4 papers, 2015 to 2026). A primary or metastatic malignant neoplasm that affects the colon or rectum. "Our results provide evidence that variants of PRLHR gene are a protective factor in colorectal cancer and variants of HSPA12A gene are a protective factor in gastric cancer in the Chinese Han population." (PMID 26302849, 2015). "We demonstrated a relationship between polymorphisms of PRLHR and HSPA12A gene and the risk of gastric and colorectal cancers in the Chinese Han population." (PMID 26302849, 2015). "This study shows that PRLHR gene is a protective factor in colorectal cancer and HSPA12A gene is a protective factor in gastric cancer." (PMID 26302849, 2015). "The aim of this study was to investigate the relationship between CHCHD3P1-HSP90AB7P, GRID1, HSPA12A, PRLHR, SBF2, POLD3, and C11orf93-C11orf92 genes and susceptibility to gastric and colorectal cancers in the Chinese Han population." (PMID 26302849, 2015). "The aim of this research was to study whether polymorphisms of CHCHD3P1-HSP90AB7P, GRID1, HSPA12A, PRLHR, SBF2, POLD3 and C11orf93-C11orf92 genes are associated with the risk of gastric and colorectal cancers in the Chinese Han population." (PMID 26302849, 2015). "In colorectal cancer, SRSF11 interacts with PAK5, promoting alternative splicing of HSPA12A, which supports proliferation and invasion." (PMID 41584036, 2026).
hepatocellular carcinoma (4 papers, 2015 to 2026). A malignant tumor that arises from hepatocytes. "Overexpression of HSPA12A might be associated with poor survival in hepatocellular carcinoma." (PMID 26302849, 2015). "Overexpression of HSPA12A can suppresses renal carcinoma cell migration while promotes hepatocellular carcinoma growth." (PMID 34412642, 2021). "It is reported that overexpression of HSPA12A in hepatocellular carcinoma tissues is significantly related to poor survival." (PMID 26302849, 2015). "When taken into account that our recent reports have shown a promoted proliferation of hepatocellular carcinoma cells by HSPA12A 53, the current data suggest that the effects of CD147 and HSPA12A on proliferation are cancer cell type- and signaling activation-dependent." (PMID 32754264, 2020). "Based on our previous unbiased screen with mass-spectrometric analysis, showing an interaction between HSPA12A and CD147 in human hepatocellular carcinoma cells, we hypothesized that HSPA12A might play a role in the regulation of CD147 during RCC migration." (PMID 32754264, 2020).
renal carcinoma (4 papers, 2020 to 2024). A carcinoma arising from the epithelium of the renal parenchyma or the renal pelvis. "Specifically, we demonstrated that HSPA12A activates aerobic glycolysis in liver cancer cells but suppresses aerobic glycolysis in renal cancer cells, suggesting that HSPA12A glycolytic regulation is tissue specific." (PMID 38421727, 2024). "In this study, we identified HSPA12A as a novel negative regulator of renal cancer cell migration and metastasis." (PMID 32754264, 2020). "However, the involvement of HSPA12A in renal disorders including renal cancers remains to be investigated." (PMID 32754264, 2020).
schizophrenia (4 papers, 2011 to 2025). A major psychotic disorder characterized by abnormalities in the perception or expression of reality. "Hspa12a encodes heat shock protein A12A which is an atypical member of the heat shock protein 70 family and has been shown to be downregulated in diseases such as ischemic stroke, schizophrenia, and renal cell carcinoma." (PMID 35179492, 2022). "Of particular interest, HSPA12A expression is decreased in the brains of patients with schizophrenia." (PMID 37580315, 2023). "Heat shock protein A12A (HSPA12A) shows decreased expression in the brains of schizophrenia patients." (PMID 37580315, 2023). "Intriguingly, evidence indicates a potential involvement of HSPA12A in the pathogeneses of psychiatric disorders because HSPA12A expression is reduced in the brains of patients with schizophrenia." (PMID 37580315, 2023). "Interestingly, Hspa12a also shows reduced expression in the prefrontal cortex of subjects with schizophrenia." (PMID 22073122, 2011). "Lastly, the heat shock protein A12A (HSPA12A, 10q25.3) is a member of the HSP70 family that regulates protein misfolding and plays a vital role in multiple neuropsychiatric conditions, including AD, major depressive disorder, bipolar disorder, and schizophrenia." (PMID 40631452, 2025).
ischemic stroke (3 papers, 2022 to 2025). A stroke disorder caused by obstruction of blood flow to the brain, due to thrombotic (local blood clot formation) or embolic (due to a blood clot or other material traveling from another site) event. "Although we have recently demonstrated that HSPA12A encodes a prosurvival pathway against ischemic stroke, the causal effects of HSPA12A in psychiatric disorders are completely unknown." (PMID 37580315, 2023). "Indeed, we recently reported that cerebral HSPA12A expression is decreased following ischemic stroke, and that HSPA12A is required for protecting brains against ischemic stroke." (PMID 37580315, 2023).
Obesity (3 papers, 2019 to 2023). Accumulation of substantial excess body fat. "In conclusion, this study demonstrates that HSPA12A is required for adipogenesis, and deficiency of HSPA12A attenuates the HFD-induced obesity and impairments of lipid and glucose." (PMID 30742088, 2019). "In this study, obese patients showed increased HSPA12A expression in WAT, while deficiency of HSPA12A in mice ameliorated HFD-induced obesity, hyperlipidemia and hyperglycemia." (PMID 30742088, 2019). "Our findings imply that HSPA12A is a novel regulator of adipocyte differentiation and diet-induced obesity through a positive feedback regulation with PPARγ." (PMID 30742088, 2019). "We have recently demonstrated that HSPA12A is required for cerebral protection and obesity development, and in particular, that HSPA12A is involved in the development of high-fat diet-induced non-alcoholic fatty liver disease, suggesting that it plays a role in the regulation of hepatic homeostasis." (PMID 32332915, 2020). "Our data strongly suggest that inhibitors of HSPA12A may be useful for the management of obesity in humans." (PMID 30742088, 2019). "HSPA12A inhibition might represent a viable strategy for the management of obesity in humans." (PMID 30742088, 2019). "Thus, HSPA12A inhibition might represent a viable strategy for the therapy of obesity in humans." (PMID 30742088, 2019). "Our study uncovers a requirement for HSPA12A in adipocyte differentiation and HFD-induced obesity." (PMID 30742088, 2019).
Sepsis (3 papers, 2020 to 2022). Sepsis is defined as life-threatening organ dysfunction caused by a dysregulated host response to infection. "To evaluate the possible involvement of HSPA12A in sepsis-induced liver injury, we measured HSPA12A expression in the livers of mice following LPS challenge." (PMID 32332915, 2020). "In conclusion, we have shown that HSPA12A protects mouse livers from the LPS-induced experimental sepsis." (PMID 32332915, 2020). "Therefore, targeting hepatocyte HSPA12A represents a viable strategy for the management of liver injury in sepsis patients." (PMID 32332915, 2020). "In the present study, we found that HSPA12A, a novel member of HSP70 family, translocates to the nucleus of hepatocytes following LPS exposure, suggesting its possible involvement in the hepatic injury during sepsis." (PMID 32332915, 2020). "However, the role of HSPA12A in sepsis-induced organ injury, including liver dysfunction, has not been established." (PMID 32332915, 2020).
Alzheimer disease (2 papers, 2014 to 2019). A progressive, neurodegenerative disease characterized by loss of function and death of nerve cells in several areas of the brain leading to loss of cognitive function such as memory and language. "This includes Alzheimer’s disease, where HSP70 has been demonstrated to have cytoprotective roles in inhibition of Aß oligomerisation and by enhancing the clearance of Aß40,41 As SorLA is the first described substrate for HSPA12A, cellular and physiological roles for HSPA12A are poorly elucidated." (PMID 30679749, 2019).
depression (2 papers, 2023 to 2025). "The effects of GSK3β inhibition on HSPA12A-maintained lactate production in hippocampal neurons prompted us to determine the effects of GSK3β inhibition on depression and anxiety behaviors in Hspa12a−/− mice." (PMID 37580315, 2023). "However, two other depression-related behavioral tests (the forced swim test and tail suspension test) revealed shorter immobility time and fewer immobility events in Hspa12a−/− mice compared to those in WT controls, suggesting an antidepressive effect of HSPA12A knockout." (PMID 37580315, 2023).
gastric cancer (2 papers, 2015 to 2018). A primary or metastatic malignant neoplasm involving the stomach. "HSPA12A encodes a protein of the HSP70 family that seems to act like a protective factor in gastric cancer." (PMID 29954368, 2018). "We genotyped “A/G” of rs1665650 in HSPA12A gene, which is mapped to chromosome 10q25.3, and associated with a decreased risk of gastric cancer." (PMID 26302849, 2015). "The genotype “A/G” of rs1665650 in HSPA12A gene was associated with a decreased risk of gastric cancer in overdominant model analysis (OR = 0.77; 95 % CI = 0.60–0.99; p = 0.038)." (PMID 26302849, 2015).
myocardial infarction (2 papers, 2022 to 2023). Gross necrosis of the myocardium, as a result of interruption of the blood supply to the area, as in coronary thrombosis. "The ERK inhibitor PD98059 attenuates the phosphorylation of VEGF and VEGFR2 expression through HSPA12A and attenuates angiogenic features in vitro; knockdown of HSPA12A in mice impairs cardiac angiogenesis after myocardial infarction and exacerbates cardiac dysfunction." (PMID 37427386, 2023). "The findings identified HSPA12A as a novel angiogenic regulator and suggest that HSPA12A might serve as an alternative approach for the management of angiogenesis-related diseases such as myocardial infarction." (PMID 35783189, 2022).
non-alcoholic fatty liver disease (2 papers, 2020 to 2024). "Meanwhile, Heat shock protein A12A (HSPA12A) is involved in the development of non-alcoholic fatty liver diseases caused by a high-fat diet, which suggests that it plays a vital role in regulating hepatic homeostasis." (PMID 39143382, 2024).
Anxiety (1 paper, 2023). Intense feelings of nervousness, tension, or panic often arise in response to interpersonal stresses. "Altogether, HSPA12A knockout resulted in multiple aspects of mood instability in mice, including anhedonia, lower locomotor activity, antidepression, and anxiety-like behaviors." (PMID 37580315, 2023). "However, Hspa12a−/− mice exhibited behaviors of mood instability (anhedonia, lower locomotor activity, antidepression, and anxiety), which were accompanied by impaired AHN, decreased CSF lactate levels, and downregulated hippocampal glycolytic enzyme expression." (PMID 37580315, 2023). "Here, we found that acute psychological stress increased HSPA12A expression in the hippocampus but not in the frontal cortex, whereas HSPA12A knockout resulted in mood instability, including anhedonia, low locomotor activity, and antidepressive and anxiety-like behaviors." (PMID 37580315, 2023).
endothelial dysfunction (1 paper, 2023). In vascular diseases, endothelial dysfunction is a systemic pathological state of the endothelium (the inner lining of blood vessels) and can be broadly defined as an imbalance between vasodilating and vasoconstricting substances produced by (or acting on) the endothelium. "Heat shock protein A12A (HSPA12A) could protect LPS-induced endothelial dysfunction from hyperpermeability and death through both ERKs and AKT-mediated signaling." (PMID 37465664, 2023).
heart failure (1 paper, 2025). Inability of the heart to pump blood at an adequate rate to meet tissue metabolic requirements. "MR analysis identified significant causal associations between the genes implicated in BW loss (ADD3, HSPA12A, SLC18A2, PDZD8, DUSP5, CASP7) as well as EF% and LV volumes (GPC6, UGGT2, SLAIN1, POU4F1, MBNL2) in BXD mice post-DOX and heart failure (HF) outcomes in humans." (PMID 40321772, 2025).
Hyperglycemia (1 paper, 2019). An increased concentration of glucose in the blood. "Intriguingly, knockout of HSPA12A (Hspa12a−/−) in mice attenuated high-fat diet (HFD)-induced weight gain, adiposity, hyperlipidemia, and hyperglycemia compared to their wild type (WT) littermates." (PMID 30742088, 2019).
ischemia (1 paper, 2024). A hypoperfusion of the BLOOD through an organ or tissue caused by a PATHOLOGIC CONSTRICTION or obstruction of its BLOOD VESSELS, or an absence of BLOOD CIRCULATION. "When MI/R caused cardiac injury, as indicated by decreased percentage of ejection fraction (EF%) and fraction shortening (FS%), HSPA12A expression levels were decreased in the infarcted myocardium during the reperfusion period following ischemia." (PMID 38421727, 2024). "The central findings of the present study are that aerobic glycolysis and H3 lactylation were inhibited and HSPA12A expression was downregulated in cardiomyocytes during reperfusion following ischemia, and that HSPA12A ablation exacerbated MI/R-induced cardiac dysfunction and remodeling." (PMID 38421727, 2024).
ischemic heart diseases (1 paper, 2022). "The findings identified HSPA12A as a novel angiogenesis activator, and HSPA12A might represent a viable strategy for the management of myocardial healing in patients with ischemic heart diseases." (PMID 35783189, 2022).
kidney cancer (1 paper, 2021). Primary or metastatic malignant neoplasm involving the kidney. "HSPA12A was mainly expressed in lung cancer and kidney cancer cell lines." (PMID 34712697, 2021).
mood disorder (1 paper, 2023). A cognitive disorder a disturbance in which the person's mood is hypothesized to be the main underlying feature. "We found that mood stress regulated hippocampal HSPA12A expression and cerebrospinal fluid (CSF) lactate content, whereas HSPA12A knockout (Hspa12a−/−) in mice caused mood disorders, impaired AHN, and decreased CSF lactate levels and hippocampal glycolytic enzyme expression." (PMID 37580315, 2023). "Taken together, HSPA12A is defined as a novel regulator of mood stability and exerts therapeutic potential for mood disorder." (PMID 37580315, 2023). "We identified hippocampal HSPA12A as a new mood stabilizer that lends support for its therapeutic potential in mood disorders." (PMID 37580315, 2023). "The present study has identified HSPA12A as a stabilizer of mood and behavior to alleviate mood disorders by maintaining GSK3β-mediated glycolysis in hippocampal neurons and thus cerebral lactate homeostasis." (PMID 37580315, 2023). "Thus, HSPA12A is considered as a new regulator of AHN and mood stabilization that may have therapeutic potential for mood disorders." (PMID 37580315, 2023).
myocardial ischemia (1 paper, 2024). A disorder of cardiac function caused by insufficient blood flow to the muscle tissue of the heart. "HSPA12A protects the heart against myocardial ischemia/reperfusion injury by maintaining aerobic glycolytic homeostasis and H3 lactylation in cardiomyocytes by increasing Smurf1-mediated Hif1&alpha; protein stabilization." (PMID 38421727, 2024). "In the present study, we report that, during reperfusion following myocardial ischemia, HSPA12A was downregulated and aerobic glycolytic flux was decreased in cardiomyocytes." (PMID 38421727, 2024).
nonalcoholic steatohepatitis (1 paper, 2020). "The HSP70 family member HSPA12A was found to increase in patients with nonalcoholic steatohepatitis (NASH) and animals fed with a high-fat diet." (PMID 33023034, 2020).
schwannoma (1 paper, 2013). A benign, usually encapsulated slow growing tumor composed of Schwann cells. "In our series, 5 HSPs were deregulated (HSPA12A: 3.31-fold, p=4.34e-4; HSPA13: 2.54-fold, p=0.0035; HSPA4L: 2.38-fold, p=1.17e-4; HSPB6: −2.19-fold, p=5.76e-4; HSPB8: −3.77-fold, p=0.001), suggesting that the CAV1/HSPs interaction may also play a role in schwannomas." (PMID 23354516, 2013).
Stroke (1 paper, 2019). Sudden impairment of blood flow to a part of the brain due to occlusion or rupture of an artery to the brain. "Long-term examination revealed impaired motor function recovery and neurogenesis in the knockout mice, suggesting a neuroprotective role of HSPA12A in stroke patients." (PMID 30679749, 2019). "In a recent study investigating the functional effect of HSPA12A in ischemic brain injury, it was shown that HSPA12A knockout mice exhibited an enlarged infarct volume and aggravated neurological deficits compared to their wild-type littermates after stroke." (PMID 30679749, 2019).
uterine corpus endometrial carcinoma (1 paper, 2021). A endometrial carcinoma (disease) that involves the body of uterus. "For example, the expression of HSPA8 and HSPH1 could be increased and related to good prognosis of patients with their mutations in uterine corpus endometrial carcinoma; HSPA12A mutation in lung adenocarcinoma could down-regulate its expression and lead to poor prognosis." (PMID 34712697, 2021).